PMS2 (PMS1 homolog 2, mismatch repair system component)
Diseases named in the same sentence as PMS2 in open-access papers (continued):
Sharing a sentence is not in itself a finding about the gene and the disease.
brain tumors (14 papers, 2014 to 2025). "Two truncating PMS2 variants, c.2007-2A>G and c.2117del, were exclusively associated with a highly penetrant phenotype in our cohort, with brain tumors as the main clinical presentation occurring before the age of 10." (PMID 41333974, 2025). "Immunohistochemical analyses (IHC) demonstrated complete loss of MLH1 immuno-expression as well as of PMS2 except for those in brain tumor." (PMID 32611331, 2020). "Carriers of biallelic MSH6/PMS2 mutations have higher rates of brain tumors and Lynch syndrome associated tumors." (PMID 32168907, 2020). "The cancer spectrum is related to the nature of the MMR gene mutated; patients with MSH6 and/or PMS2 mutations develop brain tumours within 10 years of life and over 40% of patients homozygous for PMS2 mutations develop second primary malignancies." (PMID 30459937, 2018). "In multicellular brain tumour spheroids, downregulation of PMS2 and MLH1 promoted the initiation of tumour cell formation and growth." (PMID 33986995, 2021). "In addition, those brain tumors retaining PMS2 or MSH6 expression were also identified applying the clinical scoring system." (PMID 33924881, 2021).
CMMRD syndrome (14 papers, 2017 to 2025). "The case was started on neoadjuvant chemoradiotherapy in addition to genetic testing which showed a homozygous pathogenic variant in PMS2, indicating CMMRD syndrome." (PMID 35651417, 2022). "In this CMMRD syndrome, homozygous carriers of PMS2 gene mutation develop brain cancers in the first decade of life and 40% of patients may develop a second primary tumor." (PMID 38313678, 2024). "The clinicopathological findings in our patient share multiple similarities with CMMRD syndrome, such as presentation in the first decade of life with T-LBL along with high-grade CNS glioma, with tumor cells showing loss of PMS2 expression." (PMID 40546517, 2025). "The patient was further evaluated and diagnosed with constitutional mismatch repair deficiency syndrome (CMMRD) with a homozygous deletion (chr7:6026910; delC) detected in exon 11 of the PMS2 gene." (PMID 37218666, 2024). "Of note, the majority of both CMMRD syndrome in general and CMMRD-associated AYA-CRC are caused by bi-allelic germline PVs in PMS2 (MIM *600259)." (PMID 36291559, 2022). "Taken together, the clinical and genetic findings in the entire family, the exclusion of CMMRD syndrome by absence of MSI in blood leukocytes, and the tumor mutational phenotype render overwhelming evidence of a digenic CPS due to the PMS2 and POLD1 (L)PVs in the siblings." (PMID 36291559, 2022).
rectal cancer (13 papers, 2017 to 2025). A primary or metastatic malignant neoplasm that affects the rectum. "Thus we hypothesize that the associations of ALL with endometrial and rectal cancer may be explained by germline variants in the PMS2 gene." (PMID 34117277, 2021). "Two patients had radiochemotherapy before surgery: one had rectal cancer and LS with PMS2 germinal mutation, MSI, and clonal loss of PMS2 in the tumor; the other had a pleomorphic sarcoma and LS with germinal mutation of MLH1." (PMID 34545179, 2022). "We could not identify any rectal cancer with a concurrent MLH1/PMS2 and MSH6 loss." (PMID 36387226, 2022). "Finally, a lack of the DNA mismatch repair protein PMS2 (PMS2) and reduced TDG expression in rectal cancer has been found to produce a supermutator phenotype at CpG sites." (PMID 31239841, 2019).
melanoma (12 papers, 2014 to 2026). A malignant, usually aggressive tumor composed of atypical, neoplastic melanocytes. "Immunohistochemical evaluation revealed isolated loss of PMS2 in her endometrial carcinoma, with retention of all mismatch repair genes in her thyroid and melanoma specimens." (PMID 39188332, 2024). "Specific mutations have now been correlated with high TMB, including NF1 mutations in melanoma and PMS2 mutations in melanoma and squamous cell carcinoma." (PMID 29725606, 2018). "PMS2 promoter mutations are present in ~10% of melanoma samples and ~8% of squamous cell carcinomas, meaning that, if functional, these mutations may comprise a meaningful subset of alterations in both of these diseases." (PMID 28420421, 2017). "These PMS2 promoter mutations occurred frequently in melanoma, in 10.0% of cases (173/1731)." (PMID 28420421, 2017). "We tested for co-occurrence of PMS2 promoter mutations with mutations in other genes in melanoma." (PMID 28420421, 2017). "Furthermore, the median allele frequency of PMS2 promoter mutations in melanoma is 0.26 (range 0.05–0.85), which is lower than that for BRAF V600 mutations occurring in the same tumor type (median 0.37, max 0.97)." (PMID 28420421, 2017). "The mutations in the promoter region of PMS2 are significantly associated with high tumour mutational burden (TMB), especially melanoma." (PMID 35202347, 2022). "The presence of any one of the PMS2 promoter alterations was associated with a 5.3-fold increase in median TMB when compared with PMS2 promoter wild-type samples in melanoma specimens." (PMID 28420421, 2017). "For selected mutation in melanoma (NRAS Q61K and BRAF V600E), and for each of the PMS2 promoter mutations, the median, minimum, and maximum allele fraction (fraction of reads at that position showing the mutation) and number of specimens with that mutation are provided." (PMID 28420421, 2017).
breast and ovarian cancer (10 papers, 2016 to 2026).
Fanconi anemia (10 papers, 2013 to 2025). Fanconi anemia (FA) is a hereditary DNA repair disorder characterized by progressive pancytopenia with bone marrow failure, variable congenital malformations and predisposition to develop hematological or solid tumors. "Protein interaction analysis indicates that this “genic signature” (Dclre1a, Rev1, Xpa, Pms2, Brca2, Parp2, Smc3, Nbn, Bax) is mainly involved in the Fanconi anemia pathway and homologous recombination repair." (PMID 34573315, 2021). "Other candidate genes with known roles for CSAs included GTF2H (general transcription factor IIH subunits 4 and 5), Fanconi anemia pathway genes, and PMS2, a mismatch repair gene." (PMID 34220964, 2021). "In the linear regression analysis for CSAs, two associations included a Fanconi anemia gene FANCD2 (Fanconi anemia complementation group D2) and an intronic variant for mismatch repair (MMR) pathway gene PMS2 (PMS1 homolog 2, mismatch repair system component)." (PMID 34220964, 2021). "This analysis identified several novel ATR synthetic lethal partner genes involved in DNA damage/repair including those targeting components of the HR/Fanconi Anaemia pathway (FANCE, SLX4, PALB2), DNA mismatch repair (MSH4, PMS2) and trans-lesion synthesis (RAD18) pathways." (PMID 27958275, 2016).
medulloblastoma (10 papers, 2012 to 2026). A malignant, invasive embryonal neoplasm arising from the cerebellum. "In medulloblastoma patients pathogenic variants in MLH1, MSH6 and PMS2 genes were detected previously." (PMID 28376765, 2017). "Germline defects in medulloblastoma patients were observed also in other genes cooperated with NBN in BRCA1-associated genome surveillance complex (BASC), including MSH6, PMS2 and MLH1." (PMID 28376765, 2017). "No homozygous P/LP variants were observed; however, in addition to the CMMRD patient with compound heterozygous MSH6 variants, a patient with medulloblastoma (MB, PT_2FK75B27) had two adjacent PMS2 P/LP InDels on the same allele, despite no reported CPS." (PMID 39974082, 2025). "From a genetic standpoint, TS can be divided into two subtypes: the first is manifested by the MMR gene and PMS2 with a high risk of developing GBM, and the second type is manifested by the adenomatous polyposis coli gene germline mutation with a high risk of developing medulloblastoma." (PMID 23119205, 2012). "Similarly, ATM, NBN, PALB2, PMS2, PTCH1, and SUFU are tumor suppressor and germline risk genes for medulloblastoma, but CH variants in these genes have not been found in prior studies." (PMID 32508881, 2020).
sarcoma (10 papers, 2014 to 2025). A usually aggressive malignant neoplasm of the soft tissue or bone. "We report a 9 years old female patient diagnosed with CIC rearrangement sarcoma with CIC-NUTM1 gene rearrangement and PMS2 frameshift mutation, WHO grade 4." (PMID 40255429, 2025). "Two patients (cases SLS6 and SLS23) presented loss of MLH1/PMS2 expression only in the CRC, while their sarcomas were MMR-intact (SLS6) or microsatellite stable (MSS) (SLS23)." (PMID 32659967, 2020). "PMS2-altered sarcomas did not demonstrate higher mutation count than sarcomas without PMS2 alteration (median 14.0 x 3.0, p=0.113)." (PMID 36741731, 2022). "PMS2 alterations were present in 10 patients overall, most commonly in the STS cohort (n=6), including two patients with leiomyosarcoma, two patients with sarcoma NOS, and one patient each with myxofibrosarcoma and pleomorphic liposarcoma." (PMID 36741731, 2022).
colon adenocarcinoma (8 papers, 2012 to 2026). "When absorptive cells of a crypt near a colonic adenocarcinoma are deficient in expression of Pms2, Ercc1 or Xpf, they are also often similarly deficient in all of the crypts within the tissue section." (PMID 22494821, 2012). "Subject 1 was diagnosed at age 71 with MMRd colon adenocarcinoma with loss of PMS2 staining by IHC." (PMID 36091175, 2022). "Subsequent evaluation identified colonic adenocarcinoma (Stage IIIB, MLH1/PMS2 deficiency), leading to total colectomy, hysterectomy, and bilateral salpingo-oophorectomy." (PMID 42016816, 2026).
colorectal adenocarcinoma (7 papers, 2018 to 2025). The most common type of colorectal carcinoma. "MMR-proficiency colorectal adenocarcinoma was a predictor of longer disease-free survival compared to any loss of MMR expression, especially loss of MLH1/PMS2 protein expression." (PMID 33302424, 2020).
lung carcinoma (7 papers, 2019 to 2026). "The detection of dMMR by immunohistochemistry in both the metastatic lesion and CRC led to retrospective testing, which revealed a concomitant loss of MLH1 and PMS2 in the primary lung cancer." (PMID 41613130, 2026). "In this study, we evaluated whether polymorphisms in DNA damage and repair genes (EXO1, RPA1, PMS1, and PMS2) were associated with prognosis and response to platinum-based chemotherapy in lung cancer patients." (PMID 36277983, 2022). "In this study, PMS2 amplification was identified in the cerebrospinal fluid samples of lung cancer patients with brain metastases." (PMID 39408656, 2024). "The functional pathway of PMS2 amplification of lung cancer cells is mainly enriched in thiamine, butanoate, glutathione metabolism." (PMID 38714954, 2024). "A recent study found that overexpression of PMS1 Homolog 2 (PMS2) in lung cancer cells augments their ability to survive, proliferate, and stimulates the formation of colonies within the brain." (PMID 39408656, 2024). "Tumor cells elevated expression of PMS2 possess the capacity to augment the metastatic potential of lung cancer and establish colonies within the brain through metabolism pathways." (PMID 38714954, 2024). "We examined the biological behavior of PMS2 (PMS1 Homolog 2)-amplified lung cancer cell lines through wound healing assays and migration assays." (PMID 38714954, 2024). "RNA sequencing was used to compare differentially expressed genes between PMS2 amplification and wild-type lung cancer cell lines." (PMID 38714954, 2024). "In this work, we presented a locally advanced lung cancer patient with dMMR/MSI-H/TMB-H tumor and selective loss of PMS2 by immunohistochemistry." (PMID 35116055, 2022). "At the same time, we introduced the PMS2 gene into a murine lung cancer LLC cell line." (PMID 38714954, 2024). "To investigate the role of PMS2 in brain metastasis, we tagged tumor cells with a dual luciferase labeling system to apply for tracking of tumor cells, and injected luciferase-labeled lung cancer cells into left ventricle of nude mice." (PMID 38714954, 2024). "Via in vivo and in vitro assays, we validated that PMS2 amplified PC-9 and LLC lung cancer cells had strong migration and invasion capabilities." (PMID 38714954, 2024). "In order to investigate the effect of PMS2 gene on the migration ability of lung cancer cells, we screened lung cancer cell lines by PCR and western blotting and we found PC9 lung cancer cell lines with consistently low PMS2 expressed in at the transcriptional and protein levels." (PMID 38714954, 2024). "Furthermore, when conducting RNA sequencing on lung cancer cells before and after intracardiac injection without the transfer of the PMS2 gene, it was found that there were no enriched pathways related to metabolism." (PMID 38714954, 2024).
bladder cancer (6 papers, 2019 to 2026).
colorectal tumors (6 papers, 2012 to 2022). "With this improved MLPA approach, we analyzed germline DNA from 13 patients with colorectal tumors characterized by isolated PMS2 expression loss." (PMID 22585707, 2012). "Aberrant MLPA signals indicating a deleterious PMS2 alteration were detected in three (23%) of the 13 patients with PMS2-deficient colorectal tumors." (PMID 22585707, 2012). "Somatic hypermutability and MMR deficiency-associated signatures in a colorectal tumor from an Argentine case with the NEIL1 c.506G>A variant provided critical clues to discover a large genomic deletion of PMS2 as a concomitant germline alteration in this patient." (PMID 36387175, 2022). "We selected eight such reference samples – all publicly available – and used them with this assay to study 13 patients with PMS2-defective colorectal tumors." (PMID 22585707, 2012).